CBX8 (chromobox 8)
Description:
Component of a Polycomb group (PcG) multiprotein PRC1-like complex, a complex class required to maintain the transcriptionally repressive state of many genes, including Hox genes, throughout development. PcG PRC1 complex acts via chromatin remodeling and modification of histones; it mediates monoubiquitination of histone H2A 'Lys-119', rendering chromatin heritably changed in its expressibility.
Synonyms: Pc3; hPc3; RC1
Tractability: Small molecule: a high-quality ligand is known. PROTAC: ubiquitination databases record sites on it; its protein half-life has been measured; a small molecule that binds it is known.
Target class: Epigenetic regulator; Reader; Methyl-lysine/arginine binding protein; Chromodomain
Gene: Protein-coding gene on chromosome 17 (79,792,132 to 79,801,683, reverse strand). Ensembl gene ENSG00000141570.
Subcellular location: Nucleus
Subcellular location (Human Protein Atlas): Nucleoplasm
Pathways (Reactome):
Metabolism of proteins: SUMOylation of DNA damage response and repair proteins; SUMOylation of DNA methylation proteins; SUMOylation of RNA binding proteins; SUMOylation of chromatin organization proteins; SUMOylation of transcription cofactors
Cellular responses to stimuli: Oxidative Stress Induced Senescence
Developmental Biology: Differentiation of naive CD4+ T cells to T helper 2 cells (Th2 cells)
Gene expression (Transcription): RUNX1 interacts with co-factors whose precise effect on RUNX1 targets is not known
Signal Transduction: Regulation of PTEN gene transcription
Gene Ontology:
Molecular function: histone H3K27me3 reader activity; protein binding; chromatin binding; single-stranded RNA binding; ubiquitin-protein transferase activator activity
Biological process: negative regulation of transcription by RNA polymerase II; heterochromatin formation; negative regulation of DNA-templated transcription; cellular response to hydrogen peroxide; positive regulation of cell population proliferation; positive regulation of collagen biosynthetic process; positive regulation of DNA repair
Cellular component: chromatin; nucleoplasm; nucleus; PcG protein complex; PRC1 complex; heterochromatin
Genetic constraint (gnomAD): Loss-of-function variants: 8 observed, 33.69 expected, observed/expected ratio (o/e) 0.24, 90% interval 0.14 to 0.43. The synonymous counts are far from expectation, so gnomAD's model fits this gene poorly and the ratio says little. Missense variants: 505 observed, 518.83 expected, observed/expected ratio (o/e) 0.97, 90% interval 0.9 to 1.05. Synonymous variants: 268 observed, 215.77 expected, observed/expected ratio (o/e) 1.24, 90% interval 1.12 to 1.37.
Homologues: Orthologues: chimpanzee CBX8 (99% identical), guinea pig CBX8 (94% identical), macaque CBX8 (91% identical), dog CBX8 (90% identical), rat Cbx8 (88% identical), mouse Cbx8 (87% identical), rabbit CBX8 (81% identical), pig CBX8 (54% identical), tropical clawed frog cbx8 (49% identical), zebrafish cbx8b (42% identical), zebrafish cbx8a (40% identical), Caenorhabditis elegans set-31 (17% identical), and 1 more. Paralogues in human: CBX6 (34% identical), CBX4 (25% identical), CBX2 (24% identical), CBX7 (22% identical), NPTXR (15% identical), CBX1 (13% identical), CBX3 (12% identical), CBX5 (11% identical).
Diseases named in the same sentence as CBX8 in open-access papers:
CBX8 is named in the same sentence as 64 diseases in open-access papers, as found by Europe PMC text mining. Sharing a sentence is not in itself a finding about the gene and the disease. The quoted sentences say what the papers report.
breast carcinoma (22 papers, 2014 to 2025). "Though a recent study has demonstrated that the expression of CBX8 promotes mammary tumorigenesis both in vivo and in vitro, information on 17q25 (CBX8) as a breast cancer susceptibility locus is limited." (PMID 29560110, 2018). "Studies have shown that CBX8 is overexpressed in esophageal cancer, colorectal cancer, and breast cancer, resulting in a poor prognosis." (PMID 35814427, 2022). "Accumulating evidence has revealed the involvement of CBX8 in regulatory work of different malignancies, including breast cancer, esophageal carcinoma, and HCC." (PMID 33731128, 2021). "Some emerging studies have shown some potential links between CBX8 and leukemia, hepatocellular carcinoma and breast cancer." (PMID 34567093, 2021). "We used the CPTAC dataset to analyze the CBX8 protein phosphorylation levels of five kinds of tumors (breast cancer, colon cancer, LUAD, ovarian cancer, and UCEC) and compared them with normal tissues." (PMID 34567093, 2021). "Through analysis of the CPTAC dataset, we found that CBX8 protein had higher expression in breast cancer, clear cell RCC, colon cancer, LUAD, ovarian cancer, and UCEC (all P-value < 0.001) than in related normal tissues." (PMID 34567093, 2021). "CBX8 promotes cell growth in multiple cancers including breast cancer, leukaemia, oesophageal carcinoma, colorectal and HCC." (PMID 34316702, 2021). "Emerging evidence shows that high expression of CBX8 is correlated with poor prognosis in breast cancer." (PMID 34567093, 2021). "CBX8 was found to have the ability to promote invasion and migration in breast cancer, lung cancer, and glioblastoma, and in HCC." (PMID 34046352, 2021). "CBX2, CBX4, CBX6, CBX7, and CBX8 are subunits of distinct polycomb repressive 1 complexes that have important functions in the development and progression of breast cancer." (PMID 33082469, 2020). "Collectively, the results indicated that CBX8 was upregulated in glioblastoma, breast cancer, and lung cancer." (PMID 33251331, 2020). "Here, we explored the role of CBX8 in glioblastoma, breast cancer, and lung cancer and found that the efficiency for promoting metastasis differs among cancers." (PMID 33251331, 2020). "The effect of CBX8 on metastasis was more significant in glioblastoma and breast cancer than in lung cancer." (PMID 33251331, 2020). "Functional analyses indicated that CBX8 promoted invasion and migration in glioblastoma, breast cancer, and lung cancer in vitro and in vivo." (PMID 33251331, 2020). "The role of CBX8 as an oncogene in cancer development is supported by the high expression of CBX8 in leukemia, colon, and breast carcinomas relative to normal tissues." (PMID 30718464, 2019). "In a loss-of-function screen targeting 60 epigenetic regulators, the Polycomb protein Cbx8 has been found to be a key regulator of mammary carcinoma both in vitro and in vivo." (PMID 30488017, 2018). "WDR5 associates with Cbx8, maintains histone H3K4 trimethylation at Notch-network gene promoters and is required for Notch signaling activation and breast cancer tumorigenesis." (PMID 30488017, 2018). "In agreement with this, other studies on colon, esophageal and breast cancer found that PRC1 containing CBX8 mediates oncogenic properties." (PMID 27449098, 2016). "CBX8 also acts as a key regulator of mammary carcinoma in vivo." (PMID 40175347, 2025). "In the context of breast cancer, the overexpression of CBX8 has been found to suppress WNK2." (PMID 37627077, 2023). "Many studies proved that CBX8 could promote tumor development and metastasis in many cancers, such as breast cancer, hepatocellular carcinoma, cervical cancer cell, and muscle-invasive bladder cancer." (PMID 35813444, 2022). "Finally, CBX8 was found to promote invasion and migration in several cancer types including glioblastoma, lung cancer, and breast cancer." (PMID 35155439, 2022). "A recent study indicated that high expression of CBX8 indicates a poor prognosis in breast cancer." (PMID 34567093, 2021).
breast carcinoma (continued). "Also, other CBX family members like CBX3, CBX4, CBX5, CBX6, CBX7 and CBX8 express different patterns in breast cancer compared with other cancer types cells." (PMID 29190923, 2017). "CBX8 was 2.048-fold elevated in breast cancer samples as compared with normal tissues (p=1.10E-16)." (PMID 29190923, 2017). "More importantly, CBX8 contributes to increased cancer stemness in CRC, as well as HCC and breast cancer." (PMID 35681547, 2022). "CBX8 knockdown and overexpressing cell lines were generated in glioblastoma (U-251 MG), breast cancer (MDA-MB-231), and lung cancer (A549), and CBX8 expression levels were validated by quantitative reverse-transcriptase PCR (qRT-PCR) and western blotting." (PMID 33251331, 2020). "A negative relationship between the WNK2 and CBX8 was found in the breast cancer cell line MDA-MB-231 and the insertion of this cancer cell line in a mouse model resulted in increased metastasis." (PMID 37627077, 2023). "In line with this study, CBX8 is also reported to induce stemness in HCC and breast cancer." (PMID 35681547, 2022). "CBX8 expression was higher in breast cancer and lung cancer cell lines than in non-cancer cell lines." (PMID 33251331, 2020). "Additionally, CBX8 sustains the transcriptionally active histone modification H3K4me3 at the promoters of Notch pathway-related genes and interacts with WDR5, a component of the H3K4 methyltransferase complex, thereby amplifying its role in the tumor progression of breast cancer cell lines." (PMID 40175347, 2025).
leukemia (15 papers, 2014 to 2026). A malignant (clonal) hematologic disorder, involving hematopoietic stem cells and characterized by the presence of primitive or atypical myeloid or lymphoid cells in the bone marrow and the blood. "In contrast, CBX2, CBX7, and CBX8 have oncogenic potential in hematopoiesis as they promote the survival of leukemia and lymphoma cells." (PMID 38426219, 2024). "SW2_110A displayed anti-proliferative effects in MLL-AF9 leukemia cells and demonstrated that the CBX8 chromodomain is required for CBX8-mediated HOXA9 gene activation in MLL-AF9 leukemia." (PMID 36948085, 2023). "CBX8 inhibits stress-induced premature senescence in K562 leukemia cells by regulating AKT-RB-E2F1 pathway." (PMID 36712870, 2022). "SW2_110A specifically inhibits the association of CBX8 with chromatin in cells and inhibits the proliferation of THP1 leukemia cells driven by the MLL-AF9 translocation." (PMID 34617019, 2021). "Further analysis of the Oncomine database showed that CBX8 was highly expressed in colorectal cancer, leukemia, liver cancer, lung cancer and sarcoma (all P-values < 0.05) compared with normal controls." (PMID 34567093, 2021). "The transcriptional regulation of mixed lineage leukemia (MLL)-AF9 and the occurrence of leukemia are affected by CBX8." (PMID 34567093, 2021). "CBX8 is specifically required for the development of KMT2A‐rearranged (KMT2A‐r) leukemia." (PMID 38426219, 2024). "The exact biochemical role of CBX8 in MLL-AF9 leukemia remains to be elucidated." (PMID 34617019, 2021). "Indeed, in leukemia cells Cbx8 has already been described as a component of activating complexes containing Tip60 and MLL-AF9." (PMID 25500566, 2014). "In MLL-rearranged leukemia, the MLL-AF9 fusion protein aberrantly recruits transcriptional and epigenetic modifiers, including DOT1L, BCOR, and CBX8, disrupting normal hematopoietic gene regulation." (PMID 42063817, 2026). "Knockdown of CBX8 or inhibition of the CBX8 chromodomain significantly reduces viability and HOX gene expression in MLL-AF9 leukemia cell lines." (PMID 34617019, 2021). "For example, an extensive survey of 29 chromatin regulators in the K562 human leukemia cell line included data showing that endogenous CBX2 and CBX8 had remarkably coincident binding profiles." (PMID 24485159, 2014). "Although it remains unclear whether CBX8 acts as a transcriptional activator or repressor, knockdown studies point out the importance of CBX8 in KMT2A‐r leukemia." (PMID 38426219, 2024). "It was shown that CBX8, however, might facilitate the transcriptional activity of E2F1 by enhancing the phosphorylation of AKT-p27-RB in K562 leukemia cells." (PMID 29108247, 2017).
colorectal cancer (13 papers, 2014 to 2026). A primary or metastatic malignant neoplasm that affects the colon or rectum. "IGF2BP1 specifically combines with the mature mRNA of CBX8 and promotes CBX8 production depending on the presence of m6A modifications, thereby promoting colorectal cancer growth and reducing chemotherapy sensitivity." (PMID 38102645, 2023). "For instance, knockdown of CBX8 restrained the proliferation of colorectal cancer cells, and proliferation, invasion, and cloning ability of ESCC cells (KYSE2 and KYSE510) were also suppressed by CBX8 silencing." (PMID 35814779, 2022). "We are also interested in the correlation between CBX8 and pluripotency-associated genes in NAT of colorectal cancer patients." (PMID 35681547, 2022). "CBX8 is also upregulated in colorectal cancer, and CBX8 overexpression indicates poor prognosis." (PMID 30718464, 2019). "UNC7040 disrupts the association of CBX8 with H3K27me3-rich chromatin but promotes non-specific interaction of CBX8 with nucleic acids and antiproliferative activity in diffuse large B cell lymphoma and colorectal cancer cell lines." (PMID 40302984, 2025). "This study investigated the clinical significance of CBX8 gene expression, a cancer stemness-related gene, in tumor and NAT tissue of colorectal cancer (CRC) patients." (PMID 35681547, 2022). "However, the role of CBX8 in colorectal cancer remains unknown." (PMID 25360999, 2014). "Moreover, in colorectal cancer, METTL3 targets genes such as SOX2, HK2, SLC2A1, and CBX8, inducing metastasis-related processes and activating the glycolysis pathway and cellular stemness." (PMID 38966069, 2024).
hepatocellular carcinoma (12 papers, 2019 to 2022). A malignant tumor that arises from hepatocytes. "Results revealed that high expression of CBX1, CBX2, CBX3, CBX6, and CBX8 was associated with poor survival rates of hepatocellular carcinoma patients." (PMID 35677563, 2022). "In hepatocellular carcinoma, CBX8 has been reported to exhibit oncogenic activity via AKT/β-Catenin activation, and its overexpression was inversely correlated with patient survival time." (PMID 35210369, 2022). "According to some published studies, in hepatocellular carcinoma, the proliferation, migration and invasion of hepatocellular carcinoma are affected by CBX8." (PMID 34567093, 2021). "In hepatocellular carcinoma, CBX8 upregulates EGR1 and miR-365-3p to stimulate the AKT/β-catenin pathway and shows oncogenic activity." (PMID 34395271, 2021). "Meanwhile, although the role of CBX8 in several cancers is explained such as hepatocellular carcinoma and acute myeloid leukemia, the function and association with histone modification have not been reported in pancreatic cancer yet, which needs a further exploration." (PMID 34090418, 2021). "Higher expression of CBX7 was correlated with better prognosis in hepatocellular carcinoma, whereas CBX1, CBX2, CBX3, CBX6 and CBX8 were identified as independent prognostic factors for poor overall survival." (PMID 35637952, 2022).
glioblastoma (9 papers, 2013 to 2025). The most malignant astrocytic tumor (WHO grade IV). "The balance of CBX7 and CBX8 expression is also known to play an important role in glioblastoma where CBX7 is depleted and CBX8 is abundantly expressed." (PMID 27449098, 2016). "The expression levels of CBX6 and CBX7 are downregulated, and the expression of CBX8 is upregulated in glioblastoma samples, whereas the expression of CBX2 and CBX4 remain unchanged." (PMID 24260522, 2013). "Conclusively, based on our comprehensive analysis of the expression, clinicopathological parameters, and prognostic values of eight CBX members, CBX3 and CBX8 were identified and might play pivotal roles in the tumorigenesis and progression of glioblastoma." (PMID 35210369, 2022). "Summarily, based on our comprehensive analysis about the expression, clinicopathological parameters, and prognostic values of different CBXs, only CBX3 and CBX8, which got consistent results on all these aspects, were identified as likely to take a critical part in the development of glioblastoma." (PMID 35210369, 2022). "Specifically, CBX8 plays an oncogenic role in several cancers including breast cancer and acute myeloid leukemia and is overexpressed in numerous others, such as glioblastoma multiforme (GBM)." (PMID 30597065, 2019). "We found that compared to differentiated glioblastoma cells (DGC), expression of CBX2, CBX3, and CBX5 were upregulated, while CBX1, CBX4, CBX6, CBX7, and CBX8 were downregulated." (PMID 39988672, 2025).
esophageal squamous cell carcinoma (8 papers, 2019 to 2022). Esophageal squamous cell carcinoma (ESCC) is a type of esophageal carcinoma (EC) that can affect any part of the esophagus, but is usually located in the upper or middle third. "CBX8 has been reported to promote tumorigenesis in esophageal squamous cell carcinoma and to suppress metastasis by repressing Snail." (PMID 36292141, 2022). "In the metastasis of esophageal squamous cell carcinoma, CBX8 serves as a tumor suppressor by binding with the Snail promoter and suppressing the transcription of Snail." (PMID 34090418, 2021). "Overexpression of CBX8 induces cell proliferation but inhibits cell migration, invasion, and metastasis in esophageal squamous cell carcinoma by repressing Snail." (PMID 34395271, 2021). "The CBX8 expression in esophageal squamous cell carcinoma was significantly higher than that in paracancer tissues, and the increase extent was related to the TNM stage." (PMID 34568039, 2021).
bladder cancer (7 papers, 2020 to 2022).
colon cancer (7 papers, 2020 to 2023). "In chemotherapy-resistant tissues of colon cancer, m6A-modified chromobox 8 (CBX8) expression is remarkably upregulated." (PMID 38013272, 2023). "This same gene has been demonstrated to be correlated with CBX8 levels both in colon cancer and in NAT, emphasizing the intricate interconnection between CBX8 levels, stemness, tumor progression and resistance to therapy." (PMID 35681547, 2022). "METTL3 drives the ectopic expression of CBX8 in an m6A‐dependent manner, which obviates the sensitivity of colon cancer cells to chemotherapy of CPT‐11 and L‐OHP." (PMID 33029866, 2020). "Additionally, m6A methylation of human Polycomb 3 (CBX8) increases chemoresistance in colon cancer by maintaining the stability of CBX8 mRNA.There is evidence suggesting that chemotherapeutic resistance in CRC relies on METTL3-mediated Sec62 expression." (PMID 37965577, 2023). "METTL3‐mediated m6A methylation of CBX8 mRNA and IGF2BP1‐induced mRNA stability coordinately sustain CBX expression in colon cancer." (PMID 33029866, 2020). "In addition, CBX8 recruits KMT2B (lysine methyltransferases 2B) to the LGR5 promoter, which maintains H3K4me3 status to promote LGR5 expression, resulting in increased cancer stemness and decreased chemosensitivity in colon cancer." (PMID 34090418, 2021).
lung carcinoma (7 papers, 2020 to 2023). "Elevated levels of CBX8 have been associated with the reduced expression of WNK2 and enhanced metastasis both in vitro and in vivo across various cancer cell types, including lung cancer." (PMID 37627077, 2023).